RNU6-707P (RNA, U6 small nuclear 707, pseudogene)
Gene: Small nuclear RNA gene on chromosome X (48,153,980 to 48,154,074, reverse strand). Ensembl gene ENSG00000201517.
Homologues: Orthologues: macaque U6 (78% identical), rat LOC120098057 (78% identical), dog U6 (77% identical), guinea pig U6 (73% identical). Paralogues in human: RNU6-33P (88% identical), RNU6-1 (87% identical), RNU6-11P (87% identical), RNU6-140P (87% identical), RNU6-14P (87% identical), RNU6-2 (87% identical), RNU6-37P (87% identical), RNU6-3P (87% identical), RNU6-47P (87% identical), RNU6-4P (87% identical), RNU6-5P (87% identical), RNU6-6P (87% identical), and 1286 more.